AGT (angiotensinogen)
Diseases named in the same sentence as AGT in open-access papers (continued):
Sharing a sentence is not in itself a finding about the gene and the disease.
infertile (3 papers, 2021 to 2025). "Seminal AGT levels were found to be correlated with infertility and poor sperm motility." (PMID 39598420, 2024). "Additionally, the accumulation of angiotensinogen (AGT) in the seminal plasma may be predictive of sperm motility impairment and higher levels of DNA fragmentation in spermatozoa from infertile individuals with unilateral varicocele." (PMID 41222141, 2025).
kidney stones (3 papers, 2014 to 2025). "In the present study, we compared urinary angiotensinogen levels between the patients with nephrolithiasis and healthy controls." (PMID 24818138, 2014). "Our study investigated the urinary angiotensinogen levels in nephrolithiasis patients and initially found that the UA concentrations in the patients with nephrolithiasis were significantly higher than those in normal subjects." (PMID 24818138, 2014). "The precise mechanism for the increment of renal de novo angiotensinogen generation in nephrolithiasis patients should be investigated in further studies." (PMID 24818138, 2014). "However, there were no studies that examined in detail the urinary angiotensinogen in the patients of nephrolithiasis." (PMID 24818138, 2014).
nephrocalcinosis (3 papers, 2014 to 2026). Nephrocalcinosis is a disorder that occurs when too much calcium is deposited in the kidneys. "Gene therapy resulted in normalization of urinary oxalate levels, restoration of hepatic AGT expression, and significant attenuation of renal injury and nephrocalcinosis." (PMID 41972717, 2026).
Sleep apnea (3 papers, 2014 to 2024). An intermittent cessation of airflow at the mouth and nose during sleep is known as sleep apnea. "The upregulation of angiotensinogen, AT receptors and ACE expression could play a pathogenic role in the augmented activity of carotid chemosensitive cells and the inflammation of the carotid body in intermittent hypoxia, which is relevant to the early pathogenesis in sleep-disordered breathing." (PMID 25249981, 2014).
sleep disorder (3 papers, 2023 to 2024). A change from the patient's baseline sleeping pattern, in the hours slept and/or an alteration/dysfunction in the stages of sleep. "The interruption of angiotensinogen synthesis in astrocytes in the rat brain affects the function of the locus coeruleus, which may be responsible for cognitive, behavioural, and sleep disorders." (PMID 37348034, 2023).
aortic regurgitation (2 papers, 2018). "We have also shown that both urinary angiotensinogen and intrarenal angiotensinogen levels are significantly augmented in rats with aortic regurgitation, suggesting the potential role of intrarenal angiotensinogen in the pathophysiology of cardio-renal syndrome." (PMID 29600408, 2018).
autosomal dominant polycystic kidney disease (2 papers, 2015 to 2022). Autosomal dominant form of polycystic kidney disease. "Damage to the proximal tubule or changes in megalin function will alter AGT reabsorption, and impaired AGT reabsorption has been observed in DKD and inherited kidney diseases such as Dent’s disease and autosomal dominant polycystic kidney disease (ADPKD)." (PMID 35710133, 2022).
chronic allograft nephropathy (2 papers, 2016 to 2024). "Other studies have proposed the use of TGF-β1, AGT, and EGFR mRNA levels in urine samples of KTP as timely indicators of chronic allograft nephropathy (CAN) development." (PMID 39234105, 2024).
Dent disease (2 papers, 2020 to 2022). Dent disease is a rare genetic renal tubular disease characterized by manifestations of proximal tubule dysfunction. "Remarkably, renin and angiotensinogen massively rise (up to 40-fold) in urine of patients with Dent’s disease or Lowe syndrome, and the same occurs in urine of megalin knockdown mice [15•], or after megalin inhibition with lysine." (PMID 32172431, 2020). "Furthermore, megalin determines the level of RAS components in urine, and in the absence of megalin (like in Dent’s disease or Lowe syndrome), urinary renin and angiotensinogen levels can easily rise by 2 orders of magnitude." (PMID 32172431, 2020).
esophageal cancer (2 papers, 2021 to 2023). A primary or metastatic malignant neoplasm involving the esophagus. "However, AGT mutations occurred more frequently in patients in high-incidence areas of esophageal cancer than in the normal population." (PMID 36660245, 2023).
food allergies (2 papers, 2022 to 2025). "In AD men, the MM genotype of the AGT M235T gene was found to be associated with food allergies (p = 0.004)." (PMID 40565595, 2025). "In AD men, the MM genotype of the AGT M235T gene was associated with food allergies [OR = 6.58, 95% CI 1.66–26.04, p = 0.004, sensitivity 0.833, specificity 0.568, power test 0.780]." (PMID 40565595, 2025).
Kidney Cyst (2 papers, 2015 to 2019). Abnormal fluid filled sac within the kidney, either acquired or congenital. "For example, it has been shown that kidney cyst and cystic fluid contains renin, angiotensin II (AngII), and angiotensinogen (Agt)." (PMID 25999403, 2015). "In mice with global PKD1 deficiency, although lisinopril, an ACE inhibitor, led to more profound reductions in blood pressure, compared with AGT ASO, only AGT ASO attenuated kidney cyst formation." (PMID 30530571, 2019). "Mice without cilia and PC1 demonstrated increased kidney cyst formation, systolic blood pressure, prorenin, and kidney and urinary angiotensinogen levels." (PMID 25999403, 2015).
leiomyoma (2 papers, 2019 to 2022). A well-circumscribed benign smooth muscle neoplasm characterized by the presence of spindle cells with cigar-shaped nuclei, interlacing fascicles, and a whorled pattern. "Although several genes are selectively overexpressed in leiomyomas, compared to normal myometrium, such as insulin-like growth factor-2 receptor and insulin-like growth factor binding protein, the angiotensinogen gene as a member of renin-angiotensin system has been down regulated in these tissues." (PMID 31554351, 2019).
Lowe syndrome (2 papers, 2020 to 2021). "As a human correlate, renin and angiotensinogen are also increased in the urine of patients with Lowe syndrome and Dent’s disease." (PMID 35098216, 2021).
lupus nephritis (2 papers, 2024 to 2025). Glomerulonephritis in the context of systemic lupus erythematosus. "For example, genetic variants in genes expressed in the kidney (including TNFRSF1B, KLK1, KLK3, ACE, AGT, and APOL1) may result in increased susceptibility to kidney injury and, as a result, in progression to lupus nephritis." (PMID 39124752, 2024).
pancreatic adenocarcinoma (2 papers, 2021 to 2022). "Similarly, ACE, ACE2, and AGTR1 were significant prognostic factors for overall survival (OS) in KIRC and LGG, whereas ACE, AGT, and AGTR1 were significant prognostic factors for OS in pancreatic adenocarcinoma (PAAD)." (PMID 34671200, 2021).
placental insufficiency (2 papers, 2025). Failure of the placenta to deliver an adequate supply of nutrients and oxygen to the fetus. "Our findings indicate that the activation of the thiol-switch in the circulating maternal angiotensinogen occurs at the placental level in response to oxidative stress, exacerbated by placental insufficiency." (PMID 40699774, 2025).
proliferative diabetic retinopathy (2 papers, 2021 to 2025). Advanced retinopathy due to diabetes mellitus characterized by the formation of new vessels in the retina. "A large proteomic analysis of human vitreous samples demonstrated significantly elevated AGT levels in patients with proliferative diabetic retinopathy (PDR) compared to those without DR." (PMID 40510890, 2025).
renal cell carcinoma (2 papers, 2015 to 2025). "Polymorphisms in genes of the renin-angiotensin-aldosterone system (AGTR1 and AGT) influenced renal cell cancer susceptibility." (PMID 26537097, 2015).
retinal degeneration (2 papers, 2023 to 2025). Degeneration of the retina. "The results showed that proteins like CST3, C9, and ITM2B, among others, are associated with retinal degeneration while proteins such as COL1A2, IGFBP2, and AGT, among others, are associated with diabetic complications." (PMID 37884923, 2023).
sick sinus syndrome (2 papers, 2012 to 2018). A constellation of signs and symptoms which may include syncope, fatigue, dizziness, and alternating periods of bradycardia and atrial tachycardia, which is caused by sinoatrial node dysfunction. "Distribution of genotypes and alleles of Cx40 and AGT in patients with and without sick sinus syndrome." (PMID 22242192, 2012). "Haplotype frequency estimates of AGT gene in patients with sick sinus syndrome and controls." (PMID 22242192, 2012).
systemic sclerosis (2 papers, 2015 to 2025). A chronic disorder, possibly autoimmune, marked by excessive production of collagen which results in hardening and thickening of body tissues. "Patients with diffuse cutaneous systemic sclerosis (SSc) have significantly elevated serum levels of AngII and cutaneous angiotensinogen expression, which is not expressed in healthy skin." (PMID 25949522, 2015).
T-cell lymphoma (2 papers, 2011 to 2020). "Beyond confirming our preliminary evidences, it would be of interest to study the impact of AGT expression and MGMT promoter methylation status on fotemustine activity in T-cell lymphomas." (PMID 21752099, 2011).
tonsillitis (2 papers, 2013 to 2025). Inflammation of the tonsillar tissue. "In our study, the pathway of metabolism of Angiotensinogen to Angiotensins has also been shown to be differentially expressed between OSAS and tonsillitis." (PMID 40724870, 2025).
acromegaly (1 paper, 2020). Acromegaly is an acquired disorder related to excessive production of growth hormone (GH) and characterized by progressive somatic disfigurement (mainly involving the face and extremities) and systemic manifestations. "Moreover, AGT polymorphism was associated with cardiovascular risk in patients with acromegaly." (PMID 32667032, 2020).
acute myeloid leukemia (1 paper, 2021). Acute myeloid leukemia (AML) is a group of neoplasms arising from precursor cells committed to the myeloid cell-line differentiation. "AGT was negatively related to DNMT3A/DNMT3B in acute myeloid leukemia (LAML) and to DNMT1/DNMT3B in LGG." (PMID 34671200, 2021).
ameloblastoma (1 paper, 2022). The most common odontogenic tumor, arising from the epithelial component of the embryonic tooth and usually affecting the molar-ramus region of the mandible or maxilla. "With these bioinformatic analyses it is possible that pathogenic ameloblastoma development involve these genes in intracellular regulation (AKT1, ACTC1, ADAM10, and APOA2) or for tumor microenvironment regulation (CRP, BCHE, APP, AGT)." (PMID 36553196, 2022).
anorexia nervosa (1 paper, 2016). A disorder most often seen in adolescent females characterized by a refusal to maintain a minimally normal body weight, an intense fear of gaining weight, a disturbance in body image, and, in postmenarcheal females, the development of amenorrhea. "Of those nine genes, AKAP6 and NTNG1 were genes associated with anorexia nervosa and the remaining seven (AGT, CD36, CD38, FOXP1, PPARA, PPARG and SELL) were selected for their relationship with T2D." (PMID 27483138, 2016).
bipolar disorder (1 paper, 2022). A disorder of the brain that causes unusual shifts in mood, energy, activity levels and the ability to carry out day-to-day tasks. "To illustrate the proposed meta-analysis framework, we leverage seven different European bipolar disorder (BD) cohorts, and we identify variants in the angiotensinogen (AGT) gene to be significantly associated with BD across all 7 studies." (PMID 35664319, 2022).
brain tumour (1 paper, 2004). "For the purpose of comparison, AGT in human cerebrospinal fluids (CSF) from various brain tumour patients (n=13, 0.17±0.10μg AGT equivalent ml−1, 0.23±0.12 μg AGT mg−1 protein) and in human plasma (n=12, 226.0±62.3μg AGT equivalent ml−1, 3.23±1.22 μg AGT mg−1 protein) was also measured." (PMID 14997208, 2004).
celiac disease (1 paper, 2016). An autoimmune genetic disorder with an unknown pattern of inheritance that primarily affects the digestive tract. "Angiotensin-2, or the AGT gene was more expressed in the small intestinal mucosa of celiac disease children as compared with controls." (PMID 27483138, 2016).
colorectal tumor (1 paper, 2021). "There was a large highly significant increase of 2.413 log units in AGT gene expression suggesting increased production of the angiotensinogen precursor of the angiotensin peptides in colorectal tumor tissue." (PMID 34285715, 2021). "There was also a large increase in AGT gene expression suggesting increased production of the angiotensinogen precursor of the angiotensin peptides in colorectal tumor tissue." (PMID 34285715, 2021).
dengue (1 paper, 2020). "Angiotensinogen was reported as predictive marker of shock in dengue." (PMID 32609737, 2020).
early onset hypertension (1 paper, 2024). A form of hypertension with early onset relative to normal range for a given population. "There is evidence that the M235T angiotensinogen gene variant is associated with familial early-onset hypertension." (PMID 39726943, 2024).
hemophilia B (1 paper, 2020). Hemophilia B is a form of hemophilia characterized by spontaneous or prolonged hemorrhages due to factor IX deficiency. "INS regulates vascularization; APOH, F2, and ICAM regulate platelet activation and adhesion; AGT regulates blood vessel contraction; TNF and CCL2 regulate blood chemokine in circulation; F9 regulates onset Hemophilia B, and PON1 inhibits onset cardiovascular disease." (PMID 32753925, 2020).
hydronephrosis (1 paper, 2012). Collection of urine in the renal pelvis that results in dilatation of the renal pelvis and calyces. "Mutations in the genes encoding for angiotensinogen (AGT), renin, ACE, or angiotensin II receptor type 1 (AGTR1) in mice result in severe medullary hypoplasia and hydronephrosis, a phenotype not observed in humans with AGT, renin, ACE, or AGTR1 mutations." (PMID 22685656, 2012).
insomnia (1 paper, 2023). A sleep disorder characterized by difficulty in falling asleep and/or remaining asleep. "One potential explanation for this finding could be attributed to increased levels of renin, and aldosterone in this cohort due to an activated renin-angiotensinogen-aldosterone system (RAAS) thereby supporting the link between insomnia and serious cardiac events." (PMID 37733726, 2023).
lipidosis (1 paper, 2017). "Moreover, adipocytokines IL6 and Leptin, in addition the genes, EGR1, FOS, SERPINE1, AGT and MMP2 might have great impacts on adipocyte differentiation and lipidosis." (PMID 28706200, 2017).
metastatic colorectal cancer (1 paper, 2020). "In support of our results, high protein expression of angiotensinogen in tumors from patients with metastatic colorectal cancer has been found associated with a poor response to bevacizumab combination therapy." (PMID 32133779, 2020).
morbid obesity (1 paper, 2020). An excess of body weight, normally defined as an individual with a body mass index greater than 35 or a body weight greater than one hundred percent of ideal body weight. "Moreover, patients with morbid obesity have higher plasma concentrations of renin, angiotensinogen, ACE, Ang II, and aldosterone, activating the renin–angiotensin–aldosterone system (RAAS)." (PMID 32806722, 2020).
oligohydramnios (1 paper, 2023). A lower than normal quantity of amniotic fluid in the amniotic sac as compared to normal values. "Frequently encountered oligohydramnios is explained by renal tubular dysgenesis due to hepatocyte injury and secondary reduced angiotensinogen production as early as 20 to 25 weeks of gestation." (PMID 37048762, 2023).
pancreatic diseases (1 paper, 2018). "Among the other elevated proteins, one that has been widely hypothesized to play distinct roles in pancreatic diseases is angiotensinogen." (PMID 30214418, 2018).
rectal cancer (1 paper, 2021). A primary or metastatic malignant neoplasm that affects the rectum. "Seven hub genes, including SAA1, AGT, GNG4, GAL, CXCL1, CXCL2, and CXCL3, were upregulated in rectal cancer tissues." (PMID 34269159, 2021). "Besides CXCL1, CXCL2, and CXCL3, we mined seven other hub genes related to rectal cancer, including SAA1, AGT, GNG4, SST, SSTR2, GAL, and CXCL12." (PMID 34269159, 2021).
Renal cyst (1 paper, 2024). A fluid filled sac in the kidney. "This hypothesis is supported by high renin levels, angiotensin-converting enzyme (ACE), angiotensinogen, and angiotensin II in the fluid within renal cysts." (PMID 39200287, 2024).